CRP (C-reactive protein)
Diseases named in the same sentence as CRP in open-access papers (continued):
Sharing a sentence is not in itself a finding about the gene and the disease.
Abdominal obesity (continued). "Previous studies have highlighted that visceral adipose tissue produces large amounts of interleukin-6 (IL-6), which promotes the secretion of acute-phase proteins such as C-reactive protein (CRP), and thus the levels of IL-6 and CRP are significantly increased in individuals with abdominal obesity." (PMID 38287292, 2024). "Collectively, this perturbation in monocyte biology may explain the more pro‐inflammatory phenotype in SAs compared with WEs, with studies reporting higher CRP and IL‐6 concentrations in healthy middle‐aged SA men, women, and men with central obesity." (PMID 38011590, 2023). "Furthermore, CRP concentrations were similar between WEs with central obesity and SAs who were lean." (PMID 38011590, 2023). "In addition, strong correlations were noted between CRP and central obesity measures (WC and visceral fat area) in South Asians." (PMID 37375693, 2023). "We also analyzed how gender and central obesity modulate effects on CRP." (PMID 35035976, 2022). "Also, women with central obesity have elevated oxidative stress markers (CRP) compared to men with central obesity and thus have a higher risk than men for CVD." (PMID 36304737, 2022). "In the Bangladeshi groups presented here, CRP levels were similar across the generations among individuals above the cut-off for central obesity, and it is only those individuals with a normal WC where significant differences emerged by developmental environment." (PMID 35035976, 2022). "While first-generation migrants had lower levels of salivary CRP compared to the second-generation overall, the data showed that overweight, and particularly high central obesity, appeared to mitigate the beneficial impact of the early life environment on CRP levels." (PMID 35035976, 2022). "Furthermore, the association between the high amount of sugar intake from SSBs and elevated CRP was strengthened by abdominal obesity in prediabetes (p for interaction term = 0.030)." (PMID 36613000, 2022). "In women, the only relationship observed was between abdominal obesity and very high CRP." (PMID 34440486, 2021). "The effect of DS on abdominal obesity disappeared (β = 0.08, p = 0.45) after adjustment for CVD risk factors, which suggests that the effect of DS on abdominal obesity was completely mediated by hs-CRP." (PMID 34065158, 2021). "It indicated that the effect of DS on abdominal obesity was mediated by hs-CRP." (PMID 34065158, 2021). "While, abdominal obesity was significantly associated with older age, an increased risk of atherosclerotic cardiovascular disease, higher levels of fasting glucose, TG, LDL-C, uric acid, hs-CRP, increased BPs and lower education level." (PMID 33918620, 2021). "Previous studies have suggested that this relationship might be explained by increased CRP concentrations and abnormal adipocyte function, increasing serum concentrations of free fatty acids and abdominal obesity." (PMID 34033278, 2021). "Central obesity and other components of MetS were correlated with increased CRP levels." (PMID 29382113, 2018). "Recent research shows that very highly increased high-sensitivity CRP (hsCRP >10 mg/L) are strong predictor of clinical events and also are associated with several modifiable CVD risk factors, including smoking, HDL cholesterol, and central obesity." (PMID 24955583, 2014). "It was observed that current smokers had a larger waist-to-hip ratio (an indicator of abdominal obesity) than nonsmokers and that abdominal adiposity was significantly associated with elevated CRP levels." (PMID 25105149, 2014). "However, after considering CRP levels in our study, the relationship between impaired lung function and abdominal obesity was still evident." (PMID 25299452, 2014). "In addition, increased serum CRP was positively correlated with each metabolic component and strongest with abdominal obesity." (PMID 25299452, 2014). "Other studies have shown that CRP is associated with components of MTB, like abdominal obesity." (PMID 24170724, 2013).
Abdominal obesity (continued). "The degree of central obesity seemed to be the main determinant of an increased hs-CRP level; the association with other MetS components was not strong enough to enable further discrimination." (PMID 22417460, 2012). "The relationship between central obesity and increased levels of hs-CRP has been well studied." (PMID 22417460, 2012). "On the other hand, other authors studied 70 women with pGDM 6 years after their pregnancy and found significantly higher CRP levels in women with pGDM in the presence of abdominal obesity; they also found abnormal glucose tolerance compared with the women without a history of GDM." (PMID 22550485, 2012). "In a previous National Health and Nutrition Examination Survey (NHANES) study, a clear association was established between abdominal obesity, high-sugar beverage intake, and higher levels of C-reactive protein (CRP) in study groups with and without prediabetes." (PMID 39199499, 2024). "The snack pattern showed an indirect positive effect on general and central obesity through the CRP pathway, with the indirect effect being in the opposite direction to the direct effect, implying that CRP plays a suppressive role between the snack pattern and general and central obesity." (PMID 39599620, 2024). "Additionally, 73.6% of adults with abdominal obesity had elevated CRP (p < 0.001)." (PMID 36613000, 2022). "However, the association between central obesity and GM volume was not altered when C-reactive protein, a marker of systemic inflammation, was controlled for." (PMID 35145215, 2022). "In this large-scale community-based cohort study, we found the following: I) abdominal obesity was associated with an elevated risk of CRC in both sexes, while general obesity was found to only increase the risk of CRC in men; II) TyG and CRP could raise the risk of CRC independently." (PMID 36407320, 2022). "Interestingly, a higher risk of cancer death with the highest CRP levels was also seen in men with abdominal obesity (HR: 3.43; 95% CI: 1.03–11.48 compared to low CRP) but not those without." (PMID 26632325, 2016). "Important modifiable risk factors for elevated CRP may vary by gender, and include low physical activity for men and central obesity and absence of statin use for women." (PMID 25163828, 2014). "After adjusting for risk factors, in particular abdominal obesity, glucose tolerance, HDL cholesterol, diastolic blood pressure and smoking status, CRP levels in DRUID were no longer significantly different to AusDiab, but women in both groups had higher CRP values than men." (PMID 21078191, 2010). "When abdominal obesity was absent, inflammatory proteins, such as hs-CRP and IL-6, did not increase significantly with clustering of MetS components, despite the fact that previous studies found an association between CRP and MetS." (PMID 17903275, 2007). "Abdominal obesity is characterized by an excess of visceral fat, which secretes pro-inflammatory cytokines such as TNF-α, IL-6, and CRP." (PMID 39450238, 2024). "A significantly increased risk of elevated CRP was found in populations with prediabetes who consumed a higher amount of sugar from SSBs (≥41 g/day) when compared to non-SSB consumers after controlling for abdominal obesity (aOR = 1.57, 95%CI = 1.05–2.34) (model 2)." (PMID 36613000, 2022). "The second latent profile, labeled as DysLipoproteinemia Central Obese (DLCO), contained abdominal obesity with impaired LDL-C as well as normal FBG, HDL-C, and hs-CRP." (PMID 33691729, 2021). "When the new Nordic diet was compared against the typical Danish diet among patients with abdominal obesity, all of the anthropometric indices were improved in parallel to the SBP, IR, TG, TC, and CRP levels." (PMID 34578911, 2021). "Subjects were younger and had less favorable metabolic parameters (i.e., higher abdominal obesity, increased level of TC, TG, LDL-C, fasting glucose, HOMA-IR, and CRP levels), as baseline albumin quartiles increased." (PMID 28430803, 2017).
Abdominal obesity (continued). "Allostatic load was summed using measures of central obesity, blood pressure, hypertriglyceridemia, low HDL, plasma glucose, C-reactive protein (CRP) (a marker of systemic and local inflammation) and fibrinogen." (PMID 26751953, 2016). "Among the five components of MetS, abdominal obesity, low LDL levels, and an elevated fasting glucose level are correlated with log-CRP levels." (PMID 26193292, 2015). "Only abdominal obesity, low LDL levels, and an elevated fasting glucose level are correlated with log-CRP levels." (PMID 26193292, 2015). "Age, physical inactivity, abdominal obesity, a low LDL level, an elevated fasting glucose level, uric acid and urinary albumin to creatinine ratio (ACR) were correlated with log-CRP." (PMID 26193292, 2015). "Among the five components of MetS, abdominal obesity, a low level of LDL, and an elevated fasting glucose level are correlated with the level of log-CRP." (PMID 26193292, 2015). "Haitian American participants were older (P = .032), had higher fasting plasma glucose (P = .036), and A1C (P = .016), but had lower levels of Hs-CRP (P < .001), insulin and HOMA2-IR and lower abdominal obesity (P = .030), than African Americans." (PMID 31667161, 2014). "Several potentially modifiable factors, such as lack of physical activity, weight gain, central obesity, absence of statin treatment, and high fasting blood glucose are associated with elevated CRP levels in Type 2 DM, but the strengths of these associations may vary by gender." (PMID 25163828, 2014). "In models adjusted for age and sex, ERFE remained a significant predictor for being overweight, abdominal obesity and having a CRP level of >1 mg/L, but not for hypertriglyceridemia." (PMID 41156458, 2025). "There is a positive correlation between central obesity measures (BMI, WC, and WHR) and CRP levels." (PMID 39473678, 2024). "Abdominal obesity, unfavorable lipid profiles, and evidence of chronic inflammation (higher CRP levels) were noted in patients screened by HbA1c but not by oGTT." (PMID 39121088, 2024). "Abdominal obesity, unfavorable lipid profiles, and higher CRP levels were noted in patients screened by HbA1c, but not by oGTT." (PMID 39121088, 2024). "In a subgroup analysis of individuals with normal BMI (n = 126), those with RKOA had higher VFA, more central obesity, higher levels of CRP and total cholesterol, compared with individuals without RKOA." (PMID 36307803, 2022). "The effects of central obesity on GM volume were not mediated by C-reactive protein or blood pressure, glucose, lipids." (PMID 35145215, 2022). "But limited studies examined how abdominal obesity influences the association between SSB consumption and CRP levels in populations with and without prediabetes." (PMID 36613000, 2022). "Among individuals with prediabetes, adults who consumed a high amount of sugar from SSB had a 1.57-fold higher risk to increase CRP when compared to non-SSB consumers, even after adjusting for abdominal obesity." (PMID 36613000, 2022). "An increased cystatin C level was significantly associated with older age, male gender, lack of physical activity, low HDL cholesterol, abdominal obesity, high hs-CRP, and high ACR." (PMID 33129312, 2020). "About 47% of our males and 50% of females with elevated BP were cardiometabolic abnormalities-free, i.e., insulin sensitive, not presenting central obesity, atherogenic dyslipidemia, CRP > 3 mg/L, or hyperuricemia." (PMID 32455627, 2020). "Lack of physical activity, low HDL, abdominal obesity, high hs-CRP, and high ACR were the determinants of cystatin C." (PMID 33129312, 2020). "A previous study has also reported that patients with central obesity had higher hs-CRP level than those without." (PMID 31309101, 2019). "Although abdominal obese women had higher C-reactive protein and fibrinogen plasma levels at the baseline, these are not good markers of abdominal obesity such as IL-6, TNF-α, and TNF-β." (PMID 30107482, 2019).
Abdominal obesity (continued). "Although we observed an omnibus effect of CRP on all body adiposity measures consistent with previous evidence, differences in CRP did not mediate the central obesity-fornix myelin/neuroinflammation correlations and differences in IL-8 had no overall effect." (PMID 30735826, 2019). "The prevalence of abdominal obesity was lower in the 171 patients with hs-CRP measurements than in the patients without hs-CRP measurements (13% vs 24%, P = 0.024)." (PMID 29785272, 2018). "Modifiable risks for patients with elevated CRP include suboptimal physical activity (men) and central obesity and lack of statin use (women)." (PMID 28331855, 2017). "Prevalence of abdominal obesity, serum CRP level and HOMA-IR were not significantly different between two groups in MHO class I." (PMID 28575097, 2017). "In lean groups, subjects with NAFLD were older, more central obesity, and had higher total cholesterol, triglycerides, LDL-c, fasting plasma glucose, 2 h plasma glucose, fasting serum insulin, HOMAIR, CRP, and liver enzymes and had lower adiponectin, HDL-c and eGFR (all P < 0.01)." (PMID 27885258, 2016). "No strong interaction between leptin and CRP was suggested, although among men with abdominal obesity, interaction approached statistical significance (P = 0.07)." (PMID 26632325, 2016). "In a nationally representative sample of U.S. adults, the inverse association between 25(OH)D and metabolic disturbance (i.e. fasting blood glucose, HOMA-IR, C-reactive protein) was significantly stronger among subjects with central obesity than those without." (PMID 24130687, 2013). "However, the associations of SDB/snoring with inflammatory and adipose cytokines like C-reactive protein (CRP), leptin and adiponectin were often inconsistent when taking general or central obesity into account." (PMID 22110665, 2011). "The reason why IDF definition correlated less well with arterial stiffness or elevated hs-CRP, compared to NCEP ATP III or AHA/NHLBI definition, may be that central obesity is a prerequisite factor of IDF definition." (PMID 20028565, 2009). "Abdominal obesity group presented significantly higher hs-CRP and IL-6 levels, and a lower adiponectin level than non-abdominal obesity group." (PMID 17903275, 2007). "At the end of the trial period, statistically significant net reductions in weight and central obesity, as well as in fasting blood glucose, total cholesterol, LDL-cholesterol, triglycerides, and C-reactive protein were observed in participants who received the formulation, regardless of diet." (PMID 16948861, 2006). "When comparing CRP tertiles by central obesity (yes/no) across generations, there were significant differences among those with a normal WC (χ2 = 6, n = 204, P > 0.007), but none between generations for those who fell into the category of being centrally obese (n = 248)." (PMID 35035976, 2022). "Abdominal obesity promotes increased secretion of a range of metabolites and of biologically active substances, including glycerol, FFA, inflammatory mediators (e.g. tumor necrosis factor alpha (TNFα) and interleukin-6 (IL-6)), plasminogen activator inhibitor-1 (PAI-1) and C-reactive protein." (PMID 24410812, 2014). "Importantly, the associations observed for U-LTE4 remained statistically significant also after adjustment for CRP, suggesting that U-LTE4 may have an additive value as biomarker in the context of abdominal obesity." (PMID 25437865, 2014). "However, there was a significant negative correlation between serum adiponectin and hs-CRP levels in abdominal obesity group (r = -0.23 [95%CI, -0.37 to -0.08])." (PMID 17903275, 2007). "When stratified by age (<60, 60 to 70, and ≥70 years), abdominal obesity (yes or no), hyper-hs CRP (yes or no) and Low HDL (yes or no), we could still observe a negative association between MAFLD and femoral osteoporosis, although the correlation becomes tenuous." (PMID 35846319, 2022).
Abdominal obesity (continued). "However, our findings were not completely in agreement with these previous works; the presence of central obesity in our non-MetS subjects could not lead to significantly elevate serum levels of CRP and IL-6." (PMID 29670915, 2018). "Other authors also found a negative correlation between adiponectin levels and CRP, but this correlation became nonsignificant after adjustment for BFM, the latter being explained by the finding that CRP is also related to central obesity." (PMID 22550485, 2012).